KRTAP5-7 (keratin associated protein 5-7)
Description:
In the hair cortex, hair keratin intermediate filaments are embedded in an interfilamentous matrix, consisting of hair keratin-associated protein (KRTAP), which are essential for the formation of a rigid and resistant hair shaft through their extensive disulfide bond cross-linking with abundant cysteine residues of hair keratins. The matrix proteins include the high-sulfur and high-glycine-tyrosine keratins.
Synonyms: KRTAP5.7; KRTAP5-3
Tractability: No criterion of Open Targets' tractability assessment is met for any kind of drug.
Gene: Protein-coding gene on chromosome 11 (71,527,267 to 71,528,669, forward strand). Ensembl gene ENSG00000244411.
Pathways (Reactome):
Developmental Biology: Keratinization
Gene Ontology:
Molecular function: protein binding
Cellular component: cytosol
Genetic constraint (gnomAD): Loss-of-function variants: 1 observed, 3.25 expected, observed/expected ratio (o/e) 0.31, 90% interval 0.11 to 1.38. That is too few expected variants to judge how well the gene tolerates losing a copy. Missense variants: 160 observed, 196.25 expected, observed/expected ratio (o/e) 0.82, 90% interval 0.72 to 0.93. Synonymous variants: 53 observed, 76.8 expected, observed/expected ratio (o/e) 0.69, 90% interval 0.55 to 0.87.